RAG2 (recombination activating 2)
Diseases named in the same sentence as RAG2 in open-access papers (continued):
Sharing a sentence is not in itself a finding about the gene and the disease.
encephalitis (2 papers, 2006 to 2020). An acute inflammatory process affecting the brain parenchyma. "Females with late manifestation of RAG2 variant presented with encephalitis, HSV, bronchitis, pneumonia, neutropenia and pneumonia (8b_f), local BCGitis, and failure to thrive (12_f)." (PMID 32655540, 2020). "In ICP4- virus-infected rag2-/- mice, McKrae infection progressed to fatal encephalitis by 5.7 ± 0.1 days post challenge." (PMID 16764725, 2006). "In 0--GFP-infected rag2-/- mice, McKrae infection required 9.0 ± 0.5 days to progress to fatal disease, suggesting that the ongoing innate response to 0--GFP infection delayed the progression of McKrae infection to a fatal encephalitis." (PMID 16764725, 2006).
Ewing sarcoma (2 papers, 2014 to 2023). A small round cell tumor that lacks morphologic, immunohistochemical, and electron microscopic evidence of neuroectodermal differentiation. "However, our studies underscore the utility of partially immunocompetent nude and RAG2−/− strains for study of the Ewing sarcoma immune landscape, as key elements of human disease can be captured in these models." (PMID 37615015, 2023). "Thus, although due caution must be applied, we aver that nude and RAG2−/− mice can provide useful insights into the role and regulation of innate immunity (particularly NK cells) in Ewing sarcoma pathogenesis." (PMID 37615015, 2023).
fibrosis (2 papers, 2021 to 2023). the formation of excess fibrous connective tissue in an organ or tissue in a reparative or reactive process. "Furthermore, increased IL1RL1 and decreased IFNGR1 expressions are confirmed in ILC2s from individuals with idiopathic PF, highlighting the applicability of Ifngr1-/-Rag2-/- mice as a mouse model for fibrosis research." (PMID 38097562, 2023).
gallbladder cancer (2 papers, 2021 to 2022). "It was confirmed using a RAG2-knockout porcine gallbladder cancer model with lymph node metastases that SLN mapping is effective under tumor-burden circumstances." (PMID 35053527, 2022). "In this study, we established a RAG2-KO swine gallbladder cancer model with lymph node metastases to confirm that SLN mapping is effective under a tumour burden circumstance." (PMID 33705492, 2021). "In conclusion, our dual tracer method with ICG and SPIO using a laparoscopic magnetic probe to detect the SLNs of gallbladders in healthy wild-type swine and an established RAG2-KO swine gallbladder cancer model in situ is feasible." (PMID 33705492, 2021). "Topographical distribution of the sentinel lymph nodes and metastatic lymph nodes in a RAG2-knockout swine gallbladder cancer model." (PMID 33705492, 2021).
gastric cancer (2 papers, 2018 to 2024). A primary or metastatic malignant neoplasm involving the stomach. "Exosomes derived from phosphoantigen-expanded Vδ2-T cells could cause apoptosis of Epstein-Barr virus (EBV)-associated gastric carcinoma cells and suppress the growth of EBV-associated gastric carcinoma in Rag2−/− γc−/− mice." (PMID 38302430, 2024). "To establish an invasive gastric cancer xenograft model which demonstrates invasion through the gastric wall both at local and distant sites, we utilised Rag2/GammaC double knockout mice." (PMID 29339747, 2018).
glioblastoma (2 papers, 2022 to 2025). The most malignant astrocytic tumor (WHO grade IV). "Western blotting of the pull-down samples showed that both RAG1 and RAG2 were present and remained as a complex within the glioblastoma cell line, U87, as compared to the positive control, Nalm6." (PMID 41362770, 2025). "In the present study, we have demonstrated the presence of RAG1 and RAG2 expression in multiple glioblastoma cell lines as well as glioblastoma patient samples." (PMID 41362770, 2025). "This indicates that RAG2 expression is consistently maintained at moderate to high levels in glioblastoma, while RAG1 exhibits both high and medium levels in the majority of the patients." (PMID 41362770, 2025). "In the present study, we report that RAG1 and RAG2 are differentially expressed in various glioblastoma cell lines studied and can bind and catalyze recombination between canonical RSS." (PMID 41362770, 2025). "Thus, our results suggest that RAG1 and RAG2 present in glioblastoma cells can interact and bind to DNA containing 12RSS." (PMID 41362770, 2025). "Since RAG1 and RAG2 expression was seen in glioblastoma cell lines, we wondered whether the RAGs can bind to canonical 12RSS DNA and catalyze the V(D)J recombination, as this may explain several genomic rearrangements seen during glioblastoma." (PMID 41362770, 2025). "Taken together, these results highlight a non-random and coordinated expression pattern of RAG1 and RAG2 in glioblastoma, with very few samples displaying low levels of either gene." (PMID 41362770, 2025). "The RNA-seq data analysis from 693 glioblastoma patient samples from the CGGA database showed that the vast majority of tumors expressed medium to high levels of RAG1 and RAG2, with no samples exhibiting simultaneous low expression of the two genes." (PMID 41362770, 2025).
Glucose intolerance (2 papers, 2023 to 2025). Glucose intolerance (GI) can be defined as dysglycemia that comprises both prediabetes and diabetes. "In contrast to wild-type mice, who require several months of air pollution exposure to develop a metabolic phenotype, Rag2-/- mice developed glucose intolerance after just one month of DEP administrations." (PMID 37400850, 2023). "Rag2-/- mice developed glucose intolerance already after one month of DEP exposure compared to PBS, while insulin and body weights were comparable." (PMID 37400850, 2023). "In addition, HF-HC-fed wild-type and Rag2-/- mice showed similar levels of glucose intolerance." (PMID 41362710, 2025). "On the contrary, Rag2-/- mice lacking adaptive immune cells developed pronounced gut inflammation and glucose intolerance upon oral DEP exposure." (PMID 37400850, 2023). "Hence, Rag2-/- mice were not protected from air pollution-induced glucose intolerance, indicating that air pollution-induced glucose intolerance is not mediated through mature T-/B-lymphocytes." (PMID 37400850, 2023). "Rag2-/- mice were not protected from air pollution-induced glucose intolerance." (PMID 37400850, 2023). "These mouse models have previously not shown any metabolic traits – i.e., glucose intolerance or insulin resistance – on a chow diet (CCR2-/- and Rag2-/- mice)." (PMID 37400850, 2023).
inflammatory bowel disease (2 papers, 2015 to 2022). A spectrum of small and large bowel inflammatory diseases of unknown etiology. "In this regard, the adoptive transfer of regulatory T cells reduced the onset and progress of inflammatory bowel disease (IBD) and colon cancer induced by Helicobacter hepaticus colonization in aged Rag2 (Recombination activating gene 2 protein)-deficient mice." (PMID 35794566, 2022).
intestinal infection (2 papers, 2018 to 2022). "Since IL-33 rescues RAG2-/-, but not RAG2-/- γc-/-, mice from Clostridioides difficile and amebic infection, IL-33-ILC2 exerts host protection from these intestinal infections." (PMID 35707544, 2022).
IPEX syndrome (2 papers, 2021 to 2025). "While present in almost all categories, their burden and distribution vary, with certain defects acting as clear ‘hotspots’, such as IPEX syndrome, APECED, LRBA, RAG1, RAG2, CD3γ, Helios, ARPC1B, and CD55 deficiencies." (PMID 41394846, 2025).
liver fibrosis (2 papers, 2021 to 2023). "In addition, administration of A213 to Rag2−/− mice caused significant fatty liver, liver fibrosis, and a significant increase in serum and liver palmitate concentrations, as in RORgt KI/KI mice." (PMID 33790913, 2021).
lung carcinoma (2 papers, 2017 to 2025). "In addition, they transduced T cells with one of these TCRs and adoptively transferred them to Rag2–/– mice, but they failed to see greater localization to the lung, either at baseline or in a model of lung cancer." (PMID 40626358, 2025).
malaria (2 papers, 2008 to 2025). Malaria is a serious and sometimes fatal disease caused by a parasite that commonly infects a certain type of mosquito which feeds on humans. "Since RAG2-/- are unable to control the growth of malaria parasites and generally die of a fulminating parasitaemia between 10 to 12 days post-infection measurements were taken only up to day 9 of infection, prior to the peak of infection and before anaemia was maximal." (PMID 18439291, 2008).
metastatic disease (2 papers, 2015 to 2023). "Tumor-bearing Rag2 deficient mice that were administered control treatment died of metastatic disease, whereas those treated with TDLN were cured." (PMID 26090481, 2015). "Although RAG2−/− mice do succumb to eventual end-stage metastatic disease, these results indicate that adaptive lymphocytes are not required to limit initial metastatic growth within the first 3 d of metastatic seeding." (PMID 36881866, 2023).
Obesity (2 papers, 2013 to 2022). Accumulation of substantial excess body fat. "On the other hand, adoptive transfer of small intestinal ILC2s (SI-ILC2) into Il2rg-/-Rag2-/- mice promoted HFD-induced obesity and subsequent adipose tissue inflammation." (PMID 35784368, 2022). "Obesity was induced in HFD-fed Rag2-/- mice (lacking T cells, B cells, and NKT cells but with ILCs or NK cells), but not in Il2rg-/-Rag2-/- mice (lacking all lymphocytes)." (PMID 35784368, 2022). "Interestingly, Rag2-/- mice lacking the β chain of the IL-2 receptor were less sensitive to HFD than Rag2-/- mice, implying that SI-ILC2-derived IL-2 plays an important role in the induction of obesity." (PMID 35784368, 2022).
papilloma (2 papers, 2013 to 2024). A benign epithelial neoplasm that projects above the surrounding epithelial surface and consists of villous or arborescent outgrowths of fibrovascular stroma. "To this end, we compared papilloma incidence between RAG2−/−/IL-4Rα−/− double-knockout mice and RAG2−/−/IL-4Rα+/− mice as well as papilloma incidence between RAG2−/−/IL-4Rα−/− mice and RAG2+/+/IL-4Rα−/− mice after DMBA/TPA treatment." (PMID 24403255, 2013). "The fact that RAG2−/−/IL-4Rα−/− double-knockout mice and RAG2+/+/IL-4Rα−/− both showed increased papilloma incidence suggests that IL-13 signaling neither in T cells, nor in B cells was the main reason for enhanced papilloma incidence." (PMID 24403255, 2013).
prostate carcinoma (2 papers, 2011 to 2014). A carcinoma that arises from epithelial cells of the prostate gland. "PCSD1 bone-niche model was derived from a human prostate cancer femoral metastasis resected during hemiarthroplasty and serially transplanted into Rag2−/−;γc−/− mice intra-femorally (IF) or sub-cutaneously (SC)." (PMID 25278011, 2014). "A femoral bone metastasis of prostate cancer was removed during hemiarthroplasty and transplanted into Rag2-/-;γc-/- mice either intra-femorally or sub-cutaneously." (PMID 22035283, 2011). "A prostate cancer bone metastasis specimen was obtained from a castrate-resistant patient and transplanted sub-cutaneously or intra-femorally into immunodeficient, male Rag2-/-;γc-/- mice." (PMID 22035283, 2011).
Stroke (2 papers, 2011 to 2022). Sudden impairment of blood flow to a part of the brain due to occlusion or rupture of an artery to the brain. "While 80% of the top 10 enriched pathways after stroke overlapped between WT-Tacr, Rag2-/- and WT, only 40% of pathways were identical between NSG and WT." (PMID 36569903, 2022). "BALB/Ca-RAG2-/-γc-/- mice were subjected to cauterization or thrombosis stroke model and sacrificed at different time points (48hr, 1wk, 2wk and 4wk) after stroke." (PMID 22008614, 2011). "BALB/Ca-RAG2-/-γc-/- mice were selected in this study to validate a reproducible mouse model of stroke, which would allow the use of human cells in an immune permissive milieu allowing for cell therapy studies." (PMID 22008614, 2011). "We determined in all groups, except of NSG mice, an acute deficit in the rotarod performance indicated by a ≈ 40% shorter time spent on the rod acutely after stroke (3dpi to bl: WT: −48%, p = 0.020, WT-Tacr: −35%, p = 0.048; Rag2-/- = −43%, p = 0.037; NSG = −22%, p = 0.549) with a gradual recovery." (PMID 36569903, 2022). "Therefore, we compare the stroke pathology of most popular genetic mouse models using Rag2-/- mice and NSG mice, as well as tacrolimus immunosuppressed mice, to immune competent, WT control." (PMID 36569903, 2022). "In our study, we observed marked upregulation of vascular repair in the peri-infarct regions of WT-Tacr, Rag2-/- and NSG mice compared to immunocompetent WT mice 21 days after stroke." (PMID 36569903, 2022).
T cell deficiency (2 papers, 2018 to 2020). "Subsequently, we used RAG2−/− mice to examine the impact of T cell deficiency on lung function parameters and disease activity during early and late phase of ARDS." (PMID 30466430, 2018).
T cell lymphoma (2 papers, 2012 to 2019).
uveitis (2 papers, 2020 to 2022). An inflammatory process affecting a part of or the entire uvea. "CD4+ T cells purified from naïve R161M mice or Nod2−/−R161M mice were transferred into naïve syngeneic B10.RIII Rag2−/− mice that were monitored for development of uveitis." (PMID 33106495, 2020). "In mice lacking mature T and B cells (RAG2 deficient), the impact of priming on the ocular immune response was ameliorated with significantly lower vitreous cytokine concentrations and spontaneous resolution of uveitis." (PMID 35921962, 2022).
Acute hepatitis (1 paper, 2013). Acute hepatic injury resulting from inflammation typically accompanied by increased serum alanine transaminase activity. "We evaluated the roles of RORγt-expressing cells in mouse acute hepatitis model using RORγt deficient (RORγt−/−) mice and RAG-2 and RORγt double deficient (RAG-2−/− × RORγt−/−) mice." (PMID 23626860, 2013). "We next performed CCl4- induced acute hepatitis model using RORγt−/− and RAG-2−/− × RORγt−/− mice to investigate the roles of RORγt-dependent cells in the liver except Th17 cells and NKT cells." (PMID 23626860, 2013).
acute lymphoblastic B-cell leukemia (1 paper, 2024). "A similar pattern is observed for the RAG2 gene: RAG2 somatic mutations have been reported in patients with Burkitt lymphoma, mycosis fungoides-Sezary syndrome, acute lymphoblastic B-cell leukemia, DLBCL, chronic lymphocytic leukemia, small lymphocytic lymphoma, and so on." (PMID 39026935, 2024).
airway hyperresponsiveness (1 paper, 2019). "The nasal administration of IL-2 and IL-18 induced airway hyperresponsiveness, pulmonary eosinophilia, and goblet cell hyperplasia in wild type mice, but not in Rag2-deficient mice." (PMID 30717382, 2019).
Allergy (1 paper, 2024). An allergy is an immune response or reaction to substances that are usually not harmful. "The administration of an anti-human chimeric molecule in a humanized Rag2-γc-model of HDM allergy resulted in a reduction in HDM-specific IgE antibodies in both the serum and BALF." (PMID 39769423, 2024). "Furthermore, in vivo administration of the chimeric molecules in a humanized Rag2- γc- mouse model of HDM allergy reduced allergen-specific IgE antibodies and overall inflammation in the lungs." (PMID 39769423, 2024).
anaemia (1 paper, 2008). "Circulating parasite numbers were not correlated with the severity of anaemia in either BALB/c mice or under more severe conditions of anaemia in BALB/c RAG2 deficient mice (lacking T and B cells)." (PMID 18439291, 2008). "Using RAG2-/- mice lacking T and B cells, and two P. chabaudi clones (AS and CB) of differing virulence, the data indicate that the level of anaemia does not correlate with the number of parasite-infected RBC." (PMID 18439291, 2008).
autoimmune disease (1 paper, 2023). A disorder resulting from loss of function or tissue destruction of an organ or multiple organs, arising from humoral or cellular immune responses of the individual to their own tissue constituents. "RAG2 encodes lymphoid-specific recombinase that initiates V(D)J recombination, a site-specific chromosomal rearrangement process responsible for the immense diversity of TCRs and BCRs, and mutations in RAG2 may cause autoimmune diseases." (PMID 37273692, 2023).
autoimmune hemolytic anemia (1 paper, 2024). Autoimmune hemolytic anemia (AIHA) is an autoimmune disorder in which various types of auto-antibodies are directed against red blood cells causing their survival to be shortened and resulting in hemolytic anemia. "Autoimmune hemolytic anemia developed 6 mo after HSCT in P13 with a novel RAG2 mutation." (PMID 37724703, 2024).
autoimmune thyroid disease (1 paper, 2008). Inflammatory disease of the thyroid gland due to autoimmune responses leading to lymphocytic infiltration of the gland. "Furthermore, expression of the recombination-activating genes RAG1 and RAG2 is evident in ectopic GC formed in rheumatoid arthritis and autoimmune thyroid diseases." (PMID 18716662, 2008).
bladder carcinomas (1 paper, 2013). "Conversely, we have recently observed that the adaptive immune system may promote bladder carcinoma progression in a mouse model of carcinogen-induced bladder carcinoma, since Rag2−/− mice devoid of adaptive immune system developed less advanced tumours than immunocompetent hosts." (PMID 24142880, 2013). "To determine the role of the adaptive immune system in in vivo growth of bladder carcinomas, we injected MB49 and MB49-I orthotopically in the bladder of either WT or Rag2−/− female C57Bl/6J mice, which do not contain any T or B lymphocytes." (PMID 24142880, 2013).
bowel obstruction (1 paper, 2015). "have recently published a study in which they performed bone marrow transplants from EdnrB-/- animals to Rag2-/- recipients, as well as inducing bowel obstruction in WT animals." (PMID 26061883, 2015).
Brain tumors (1 paper, 2023).
chronic granulomatous disease (1 paper, 2022). Chronic granulomatous disease (CGD) is a rare primary immunodeficiency, mainly affecting phagocytes, which is characterized by an increased susceptibility to severe and recurrent bacterial and fungal infections, along with the development of granulomas. "Similar to SCIDs, other types of PIDs that can be treated by allo-HSCT are in principle eligible for autologous HSCs gene therapy, such as Wiskott-Aldrich syndrome (WAS), chronic granulomatous disease (CGD), recombination activating gene severe combined immunodeficiency (RAG1, RAG2) and so on." (PMID 35782737, 2022).
chronic leukemia (1 paper, 2016). A slowly progressing leukemia characterized by a clonal (malignant) proliferation of maturing and mature myeloid cells or mature lymphocytes. "Using Partek Genomics Suite 6.6 we examined the relationship between expression of RUNX1 and RAG1/RAG2 expression in a panel of acute and chronic leukemias from the MILE study (Microarray Innovations in LEukemia), a global microarray study comprising gene expression analysis of > 4000 patients." (PMID 27056890, 2016).